TNF (tumor necrosis factor)
Diseases named in the same sentence as TNF in open-access papers (continued):
Sharing a sentence is not in itself a finding about the gene and the disease.
inflammatory bowel disease (continued). "Beyond these genetic considerations, the observation that many patients who developed HSP while receiving TNFα antagonists were being treated for inflammatory bowel disease is provocative." (PMID 27529048, 2016). "Friedrich and colleagues showed that IL-17A strongly induced TNF-α expression in inflammatory bowel disease." (PMID 27190491, 2016). "TNFα and IFNγ are proinflammatory cytokines involved in mediating the intestinal epithelial barrier dysfunction observed in inflammatory bowel diseases, and numerous studies have demonstrated their role in disruption of epithelial apical junction structure." (PMID 27119373, 2016). "Tumor necrosis factor-α (TNFα) inhibitor therapy has signified an important milestone in the fight against many rheumatological disorders and inflammatory bowel disease (IBD)." (PMID 27529048, 2016). "The ‘Costs Of Inflammatory bowel disease in the Netherlands’ or COIN-study has been initiated to generate longitudinal cost data in order to assess the impact of anti-TNF therapy on IBD-related costs." (PMID 27099937, 2016). "LPS-induced cytokines IL-1β, IL-6, and TNFα, which are also expressed in inflammatory bowel disease, are reported to down-regulate PXR and CYP genes in vivo." (PMID 27760163, 2016). "Blood levels of both TNF-α and the soluble form of tumour necrosis factor receptor 1 (sTNFR1) are increased among inflammatory bowel disease patients." (PMID 26925234, 2016). "We mailed the survey to parents of children with juvenile idiopathic arthritis or inflammatory bowel disease who had initiated treatment with TNF-α inhibitors in the prior 2 years." (PMID 27641835, 2016). "The last known example is an ongoing clinical study using a recombinant L.lactis, AG014, which secretes anti-TNF-alpha Fab to treat inflammatory bowel disease." (PMID 27142045, 2016). "Anti-TNF-α agents are biological compounds which induce remission by reducing inflammation and providing tissue healing effect especially in inflammatory bowel diseases." (PMID 27143962, 2016). "Yearly, 200 million Euros are spent on anti-tumour necrosis factor inhibitors (anti-TNF) for inflammatory bowel diseases (IBD) in The Netherlands alone, of which 90 % is for CD and 36 million Euros of that is for fistulising CD." (PMID 26289163, 2015). "Targeting of TNFα with antibodies has been successfully used in the clinical treatment of inflammatory bowel disease for many years, highlighting the importance and clinical relevance of TNFα’s function in intestinal inflammation." (PMID 26589571, 2015). "Tumor necrosis factor-α inhibitors, such as adalimumab or infliximab, have been shown to be helpful with refractory disease, especially in patients with inflammatory bowel disease." (PMID 26327988, 2015). "The differentiated macrophages are potent producers of key inflammatory cytokines such as TNFα, IL-1β and IL-6 in inflammatory bowel disease 50,51." (PMID 25754842, 2015). "For example, some patients with inflammatory bowel disease lose responsiveness to continued infliximab administration in the presence of high levels of TNF-α neutralizing activity induced by the previously active drug." (PMID 25759761, 2015). "TNF-α expression is elevated in affected mucosal areas of inflammatory bowel disease (IBD) patients and in the active disease regions in animal models of intestinal inflammation." (PMID 26523550, 2015). "Infliximab, an antibody against tumor necrosis factor alpha, is used to treat inflammatory bowel disease and has well-established efficacy and proven safety." (PMID 26518665, 2015). "Inflammatory bowel disease (IBD) is associated with prolonged, excess secretions of Tumor Necrosis Factor (TNF)." (PMID 25775453, 2015). "TNF-α/TNFR-1 signaling has been reported to act as an endogenous tumor promoter for colon carcinogenesis in inflammatory bowel disease (IBD)." (PMID 25083765, 2014).
inflammatory bowel disease (continued). "Infliximab, a TNF-α inhibitor, is a potent anti-inflammatory drug in the treatment of inflammatory bowel diseases." (PMID 24762063, 2014). "This would be consistent with studies indicating the leading role of TNF-α in intestinal homeostasis, gut barrier integrity, and pathogenesis of inflammatory bowel disease." (PMID 25203742, 2014). "Drugs for inflammatory bowel disease include aminosalicylic acid, corticosteroids, immunosuppressant, and anti-TNF agents." (PMID 24963213, 2014). "This limits external validity of our findings, as anti-TNF-α agents are also used for treatment of other autoimmune conditions, such as inflammatory bowel diseases, and are part of chemotherapeutic protocols in treatment of B-cell lymphomas." (PMID 25114684, 2014). "In previous studies, the paracellular channel claudin-2 has been reported to be induced by tumor necrosis factor α (TNFα), which explains e.g., the pathomechanism of inflammatory bowel diseases." (PMID 25009499, 2014). "Adalimumab (Humira®), a fully human recombinant antibody specific for tumor necrosis factor- α, is approved for treatment in patients with Inflammatory Bowel Disease like ulcerative colitis or Crohn’s disease." (PMID 24400722, 2014). "Interleukin 6 (IL-6) and tumor necrosis factor alpha (TNFα) are proinflammatory cytokines that play a critical role in inflammatory bowel disease, as well as in colorectal tumorigenesis." (PMID 24120915, 2014). "Of these latter four studies, one study addressed anti-D IgG dosing, one addressed anti-tumor necrosis factor for inflammatory bowel disease, and two modeled activities of CYP enzymes." (PMID 24575394, 2014). "Many of those reported cases that lead the FDA to place a black box warning on TNF-alpha inhibitors were in children with inflammatory bowel disease rather in JIA." (PMID 25174953, 2014). "TNF-α levels are elevated in both human inflammatory bowel diseases and animal models of intestinal inflammation." (PMID 24830946, 2014). "Inflammatory bowel disease (IBD) is a TNF-dependent, immune-mediated disease resulting from a disturbed interaction between gut microbiota and mucosal cells in genetically susceptible hosts." (PMID 24339869, 2013). "Tumor necrosis factor antagonists (anti-TNFa) are an established therapeutic option for several autoimmune and inflammatory bowel diseases." (PMID 23762678, 2013). "Like many autoimmune diseases, the inflammation in inflammatory bowel disease (IBD) has been linked to upregulation of proinflammatory cytokines, such as TNFα, and nuclear translocation of the proinflammatory transcription factor complex NFκB." (PMID 23557064, 2013). "On the other hand, IL-6 and tumor necrosis factor α (TNF-α) has been shown to play an important role in the pathogenesis of inflammatory bowel disease." (PMID 24001404, 2013). "Monoclonal antibodies against tumor necrosis factor alpha (anti-TNFα), such as infliximab and adalimumab, have recently been used to treat inflammatory bowel disease." (PMID 25374717, 2013). "The importance of TNFα in inflammatory bowel disease is illustrated by the efficacy of anti-TNFα monoclonal antibodies in treating Crohn’s disease and ulcerative colitis." (PMID 23866118, 2013). "It is believed that inflammatory cytokines like TNF-α play a major role in the pathophysiology of inflammatory bowel diseases, and antibodies directed at either TNF-α or its receptor have proven to be effective therapies (reviewed in:)." (PMID 24098382, 2013). "Studies in inflammatory bowel disease demonstrated an impaired IL-4 mediated down-regulation of IL-1b, TNF alpha, and therefore leading to uncontrolled pro-inflammatory cytokine release." (PMID 23472217, 2013). "A study with children with inflammatory bowel disease showed that patients receiving anti-TNF therapy were less likely to be seroprotected against B strain." (PMID 23510667, 2013).
inflammatory bowel disease (continued). "Numerous studies have demonstrated that TNF is tightly implicated in the pathogenesis of inflammatory diseases and autoimmunity such as rheumatoid arthritis, multiple sclerosis and inflammatory bowel diseases (IBD)." (PMID 23285227, 2012). "Biological drugs such as monoclonal anti-TNF-α antibody (infliximab and adalimumab) have been recently introduced in the therapy of relapsing inflammatory bowel disease with encouraging results in the maintenance of remission." (PMID 23259641, 2012). "For example, targeted deletion of the ARE in TNFα in mice leads to chronic inflammatory arthritis and Crohn’s-like inflammatory bowel disease." (PMID 22761847, 2012). "Reactive oxygen species and pro-inflammatory cytokines such as tumor necrosis factor α (TNFα), both of which are increased during active inflammatory bowel disease, promote cellular injury and autophagy via mitochondrial damage." (PMID 22363587, 2012). "Dysregulation of TNF-α in lamina propria macrophages (LPM) is a feature of inflammatory bowel diseases (IBD)." (PMID 21984950, 2011). "The aims of this study were to compare preferences in Inflammatory Bowel Disease (IBD) patients for two currently available anti-TNF agents and the reasons for their choices." (PMID 20064220, 2010). "Bacteria increase TNF-α expression in a variety of human diseases including infectious diseases, inflammatory bowel diseases, and cancer." (PMID 20704730, 2010). "The Food and Drug Administration made their decision based on a review of 48 cases of malignancies identified worldwide in children treated with tumor necrosis factor inhibitors for inflammatory bowel disease, sarcoidosis, and juvenile idiopathic arthritis." (PMID 20712883, 2010). "TNF inhibitory strains of L. reuteri reduced inflammation in a H. hepaticus-induced murine model of inflammatory bowel disease." (PMID 19210794, 2009). "Neutrophils and TNFα are two major elements known to be involved in inflammatory bowel diseases (IBD) and excessive production of ROS and release of degradative enzymes by neutrophils have been implicated in IBD." (PMID 19649246, 2009). "Treatment of mice with anti-TNFα suppresses pathogen induced inflammatory bowel disease and inflammation triggered cancer." (PMID 18698347, 2008). "Anti-tumor necrosis factor treatments for inflammatory bowel disease face challenges like primary nonresponse and secondary loss of response, often due to antidrug antibodies that increase drug clearance." (PMID 41759997, 2026). "Additional research is required to ascertain if the newly developed vaccines may enhance immunogenicity in specific population groups, including patients with inflammatory bowel disease, particularly those receiving anti-TNF biological therapy." (PMID 40077070, 2025). "Furthermore, TNFα inhibitors are approved for use in inflammatory bowel diseases, including Crohn’s disease and ulcerative colitis." (PMID 40676697, 2025). "Patients with inflammatory bowel disease may develop infective pneumonia after using tumor necrosis factor-α inhibitors(TNFis)." (PMID 40763141, 2025). "Moreover, it has been demonstrated that ABZ enhances the clinical efficacy of anti-TNF (tumor necrosis factor) therapy in inflammatory bowel diseases." (PMID 41012470, 2025). "Tumor necrosis factor alpha inhibitors (TNFi) are biologic drugs that target TNFα, a key pro-inflammatory cytokine, to suppress disease activity and alleviate symptoms of various autoimmune diseases, including inflammatory bowel disease." (PMID 40469293, 2025). "Immune-related pathways included the following: inflammatory bowel disease (bbub05321), TNF signaling pathway (bbub04668), NF-kappa B signaling pathway (bbub04064), Toll-like receptor signaling pathway (bbub04620), and C-type lectin receptor signaling pathway (bbub04625)." (PMID 41007947, 2025).
inflammatory bowel disease (continued). "A systematic review and meta-analysis of RCTs demonstrated that curcumin was able to block NF-κB, a nuclear transcription factor that regulates the effect of TNF-α, thus lowering its concentrations, with potential efficacy against several inflammatory diseases, including inflammatory bowel disease." (PMID 40805976, 2025). "Furthermore, exosomes from human umbilical cord mesenchymal stem cells reduced the severity of inflammatory bowel disease in mice by increasing IL-10 levels and decreasing TNF-α, IL-1β, and IL-6 in the colon tissues." (PMID 40822681, 2025). "TNF-α is a pleiotropic factor involved in acute and chronic inflammatory and anti-tumor responses, and its inhibitors have been widely used in the treatment of inflammatory bowel disease." (PMID 39926427, 2025). "More recently, it was shown that CDK9 inhibition, by suppressing IFN-γ and TNF-α production in both murine and human CD4+T cells, led to potent repression of the genes responsible for the pro-inflammatory signaling, in a model of anti-TNF-resistant Inflammatory Bowel Disease." (PMID 39800748, 2025). "While TNF-α inhibitors are widely used to treat multiple inflammatory conditions, including inflammatory bowel disease and inflammatory spondyloarthropathy, there is a growing body of literature documenting paradoxical reactions, such as drug-induced sarcoidosis." (PMID 40351964, 2025). "Cytokines, including IL‐1β, IL‐6, and TNF‐α, are expressed at relatively higher levels in the intestinal tissues of patients with UC, and MPO‐mediated damage is associated with some disorders in people, including inflammatory bowel disease." (PMID 40586619, 2025). "However, excessive or chronic TNF activity is characteristic in autoimmune diseases, such as rheumatoid arthritis and inflammatory bowel disease, where it drives tissue damage and systemic inflammation." (PMID 41376630, 2025). "Alkaline protease secreted by Aspergillus oryzae has anti-inflammatory activity, which may be useful for treating TNF-α-dependent inflammatory bowel diseases." (PMID 39545259, 2024). "In their retrospective report on the association of osteonecrosis of the jaw in patients being treated with TNF-α inhibitors, Brijs and colleagues reviewed 2,701 patients with inflammatory bowel disease (IBD) and cross-matched them with patients who met the criteria for MRONJ." (PMID 39045331, 2024). "These consecutive occurrences lead to the activation of the pro-inflammatory cytokines, IL-1β, IL-6, and TNF-α, ultimately resulting in the deterioration of the intestinal epithelial cell barrier and significantly contributing to the pathogenesis of inflammatory bowel disease." (PMID 38772090, 2024). "Furthermore, the TNF pathway, IL-23/IL-17 pathway, JAK-STAT pathway, and ROR-γT/Th17 axis represent common pathogenic pathways between PsO and inflammatory bowel diseases." (PMID 39119335, 2024). "In line with this, the beneficial effects of the ethanolic extract of T. polium in an animal model of acute inflammation, and extract of T. persicum in animal model of inflammatory bowel disease were accompanied by high expression of IL-10 and low expression of TNF-α and IL-1β." (PMID 39452128, 2024). "Furthermore, inflammatory bowel disease is known to promote osteoporosis, probably via TNF-α and other pre-inflammatory cytokines." (PMID 38892677, 2024). "Moreover, efforts have been made to detect genetic polymorphisms with the aim of predicting early response to anti-TNF drugs in inflammatory bowel disease." (PMID 39062093, 2024). "Firstly, we evaluated whether irisin could modulate the expression levels of the pro-inflammatory cytokine TNFα, as previous preclinical studies showed a potent inhibitory effect of irisin on its expression in a rat model of inflammatory bowel disease." (PMID 36768133, 2023).
inflammatory bowel disease (continued). "Patients with inflammatory bowel diseases (IBD) treated with anti-tumor necrosis factor (TNF) and patients with multiple sclerosis (MS) or rheumatic disease receiving treatment with anti-CD20 therapies showed impaired humoral immune responses directly after infection." (PMID 37198536, 2023). "It has recently been reported that intravenous ustekinumab, which is an anti-IL-12 antibody, induces response and remission in patients with moderately to severely active Crohn’s disease, an inflammatory bowel disease (IBD) that is refractory to TNF-α antagonists." (PMID 37833247, 2023). "In their study of inflammatory bowel diseases in humans, the researchers found that the expression of the inflammatory cytokines IL-6, TNF-α, and IL-1β were, respectively, upregulated 2.266, 0.962, and 3.468 fold, in both Crohn’s disease and ulcerative colitis compared to healthy individuals." (PMID 38116527, 2023). "Given the potential pathophysiological connection between PD and inflammatory bowel disease (IBD), they evaluated the incidence of PD in IBD patients and investigated whether anti-tumor necrosis factor (anti-TNF) treatment for IBD affected the risk of developing PD." (PMID 37441339, 2023). "For example, supplementation with SCFAs for kidney and liver diseases, inflammatory bowel disease, and colon cancer reduced the pro-inflammatory mediators, tumor necrosis factor alpha (TNFα), interleukin-6 (IL-6), and C-reactive protein, as well as disease progression." (PMID 37432606, 2023). "It has been reported that LPS could stimulate the TLR4-NF-κB signaling pathway to induce the release of TNF-α, IL-1β, and IL-6, which are inflammatory cytokines in inflammatory bowel disease." (PMID 37125181, 2023). "DEGs were mainly enriched in 977 GO terms, such as regulation of signalling receptor activity (BP), specific granules (CC), and cytokine activity (MF); they were significantly involved in 27 KEGG pathways, such as the TNF signalling pathway and inflammatory bowel disease." (PMID 37649561, 2023). "TNF-α is also implicated in the pathogenesis of several immune-mediated inflammatory disorders (IMID), including juvenile idiopathic arthritis (JIA) and inflammatory bowel disease (IBD), where high concentrations of TNF-α lead to chronic inflammation and tissue damage." (PMID 36335186, 2023). "Patients with inflammatory bowel disease with Anti-TNF agents were less likely to develop CRC." (PMID 38041080, 2023). "In around 5-20% of patients with inflammatory bowel disease, eczema may develop as a side effect of anti-TNF therapy (IBD)." (PMID 37954750, 2023). "We previously highlighted the need for a third vaccine booster dose in patients with inflammatory bowel diseases (IBDs) treated with anti-TNF-α due to the sharper decline in their serologic response compared to patients not treated with anti-TNFα and healthy controls (HCs)." (PMID 37515078, 2023). "In terms of its epithelial barrier function, zinc could be used as an alternative to the use of steroids and anti-tumor necrosis factor modalities for treating inflammatory bowel disease (IBD)." (PMID 37836377, 2023). "The KEGG analysis also revealed a marked induction of inflammation and cytokine pathways, including the cytokine–cytokine receptor interaction, NF-κB signaling pathway, IL-17 signaling pathway, TNF signaling pathway, Toll-like receptor signaling pathway and inflammatory bowel disease." (PMID 37628738, 2023). "These anti-TNF-α monoclonal antibodies have been demonstrated to be effective in RA, juvenile idiopathic arthritis, psoriatic arthritis, ankylosing spondylitis, and inflammatory bowel disease, and each has been clinically applied." (PMID 38004064, 2023). "Vedolizumab, which is a monoclonal antibody that selectively binds to α4β7 integrin in the gastrointestinal system, may be an effective and safe treatment alternative in those with anti-tumor necrosis factor-resistant inflammatory bowel disease." (PMID 35946879, 2022).